CCL27 (C-C motif chemokine ligand 27)
Description:
Chemotactic factor that attracts skin-associated memory T-lymphocytes. May play a role in mediating homing of lymphocytes to cutaneous sites. Binds to CCR10.
Synonyms: CTACK; ILC; SCYA27; ALP; skinkine; ESkine; PESKY; CTAK
Tractability: Antibody: its Gene Ontology location is reachable by antibodies, with high confidence; UniProt places it where antibodies can reach, with medium confidence; UniProt predicts a signal peptide or a membrane-spanning region. PROTAC: ubiquitination databases record sites on it.
Gene: Protein-coding gene on chromosome 9 (34,661,880 to 34,664,048, reverse strand). Ensembl gene ENSG00000213927.
Subcellular location: Secreted
Pathways (Reactome):
Signal Transduction: Chemokine receptors bind chemokines; G alpha (i) signalling events
Gene Ontology:
Molecular function: CCR3 chemokine receptor binding; protein binding; chemokine activity; CXCR chemokine receptor binding; chemokine receptor binding
Biological process: antimicrobial humoral immune response mediated by antimicrobial peptide; cell-cell signaling; cellular response to lipopolysaccharide; chemotaxis; immune response; inflammatory response; neutrophil chemotaxis
Cellular component: extracellular region
Genetic constraint (gnomAD): Loss-of-function variants: 12 observed, 9.98 expected, observed/expected ratio (o/e) 1.2, 90% interval 0.76 to 1.81. That is too few expected variants to judge how well the gene tolerates losing a copy. Missense variants: 130 observed, 136.91 expected, observed/expected ratio (o/e) 0.95, 90% interval 0.82 to 1.1. Synonymous variants: 49 observed, 56.55 expected, observed/expected ratio (o/e) 0.87, 90% interval 0.69 to 1.1.
Homologues: Orthologues: chimpanzee CCL27 (100% identical), macaque CCL27 (96% identical), pig CCL27 (71% identical), mouse Ccl27b (61% identical), guinea pig CCL27 (60% identical), mouse Ccl27a (54% identical), rat Ccl27 (54% identical), mouse Ccl27al (54% identical), zebrafish ccl27a (21% identical), zebrafish ccl27b (20% identical). Paralogues in human: CCL28 (29% identical).
Diseases named in the same sentence as CCL27 in open-access papers:
CCL27 is named in the same sentence as 133 diseases in open-access papers, as found by Europe PMC text mining. Sharing a sentence is not in itself a finding about the gene and the disease. The quoted sentences say what the papers report.
psoriasis (29 papers, 2016 to 2026). An autoimmune condition characterized by red, well-delineated plaques with silvery scales that are usually on the extensor surfaces and scalp. "TNFRSF14 has been associated with proinflammatory factors in tumors and has poor prognosis for follicular lymphoma, while CCL27 has been associated with inflammatory skin diseases like atopic dermatitis, contact dermatitis, and psoriasis, and increased CCL27 secretion is shown to cause inflammation." (PMID 39038097, 2024). "Moreover, ligands for CCR4—CCL17 and CCL22, and CCR10—CCL27 have been associated with AD, psoriasis, cutaneous lymphomas, and systemic sclerosis." (PMID 37371632, 2023). "Elevated CCL27 levels have been reported in the sera of patients with various skin diseases, such as contact dermatitis, psoriasis, and atopic dermatitis, all of which show fluctuating CCL27 expression." (PMID 41301909, 2025). "It is an intriguing finding that CCL27 expression of keratinocytes was increased in AD but decreased in psoriasis." (PMID 35774389, 2022). "Future studies should investigate disease‐specific biomarkers, such as NOS2 (psoriasis) and CCL27 (eczema) in different palmar skin diseases." (PMID 32333380, 2020). "Specifically, CCL27 helps in lymphocyte adhesion in the skin, leading to pathological inflammatory skin diseases such as psoriasis, atopic dermatitis, mastocytosis and drug induced cutaneous reactions." (PMID 30214382, 2018). "Additionally, markers like NOS2 and CCL27 (CTACK) have shown significant utility in distinguishing AD from psoriasis." (PMID 40141720, 2025). "CCL27-knockout mice have overreactive skin inflammatory responses in a model of psoriasis." (PMID 37831367, 2024). "First, chemokine CCL27 played an essential role in psoriasis." (PMID 38238429, 2024). "Such interactions may explain the co-occurrence of depression and "psychocutaneous disorders" like psoriasis, which is accompanied by elevated CCL27 levels." (PMID 38538641, 2024). "This contradictory result suggested that CCL27 might serve as a molecular marker for differentiating psoriasis and AD." (PMID 35774389, 2022). "CCL27, also called cutaneous T-cell attracting chemokine (C-TACK), is mostly known to cause T-cell mediated skin inflammation and high serum levels are of prognostic relevance in patients suffering from psoriasis and atopic dermatitis." (PMID 27732933, 2016). "In addition, the different expression locations of CCL27 (expressed in the nucleus of eczema and the cytoplasm of psoriasis lesion) could distinguish eczema from psoriasis." (PMID 36465933, 2022). "CCR10/CCL27–CCL28 help maintain homeostasis yet can drive pathology: inflammatory dermatoses (atopic dermatitis, psoriasis, allergic contact dermatitis) show abundant CCR10 T cells and elevated CCL27/CCL28, consistent with selective Th recruitment." (PMID 41050670, 2025). "A plausible model is dynamic, context-dependent control: Th2-skewed AD upregulates CCR10/CCL27, whereas psoriasis (Th1/Th17/Th22) shifts to other chemotactic cues; notably, CCR10 marks Th22 enriched in psoriasis." (PMID 41050670, 2025). "Although several chemokines, such as CCL13, CXCL12, CXCL10, CCL27, and CCR6, have been identified in the context of psoriasis, CXCL10, in particular, has been suggested as a biomarker for psoriasis progression." (PMID 38829444, 2024). "SerpinB7 knockdown in HaCaT cells drastically increased the expression of psoriasis-related chemokines (CCL20, CCL27, CXCL1, CXCL2) and antimicrobial peptides LL37 and S100A8 in the M5-stimulated in vitro psoriatic model." (PMID 35864103, 2022). "In human skin, patients with psoriasis expressed a higher level of CCL27, a ligand of CCR10, compared to healthy controls, indicating that the CCR10/CCL27 signal facilitates the development of psoriasis." (PMID 34831296, 2021).
psoriasis (continued). "CTACK, also known as CCL27, was originally described as a CC chemokine receptor family member found in keratinocytes in psoriasis and other inflammatory and hyperproliferative skin conditions." (PMID 34158044, 2021). "Absence of the chemokine CCL27 in a knock-out mouse model results in an overactive cutaneous inflammatory response in the well-established model of imiquimod-induced psoriasis." (PMID 40873573, 2025). "Therefore, potential diagnostic biomarkers have been proposed to improve diagnosis by differentiating AD and psoriasis in patients with psoriasiform dermatitis, namely nitric oxide synthase 2 (NOS2) and CTACK/CCL27." (PMID 36012878, 2022). "However, in mouse models of inflammation, a decrease in the number of CCR10+ ILC in the skin has been reported, in addition to a decreased expression of CCL27 in psoriasis." (PMID 28303135, 2017). "In this report, we propose that CXCR4-SDF-1 is an alternative mechanism in psoriasis (and inflammatory conditions), which may explain the presence of ILC and cytokine production in psoriasis patients even in the absence of CCL27." (PMID 28303135, 2017).
atopic dermatitis (19 papers, 2015 to 2025). "Particularly, stimulation with the allergic inflammatory milieu induced a strong upregulation of CCL27, the cutaneous T cell-attracting chemokine which is one of the main cytokines involved in atopic dermatitis (AD) pathogenesis." (PMID 35913947, 2022). "The CCR10/CCL27 axis is important for the skin during homeostatic conditions, and circulating CCL27 is increased in children with atopic dermatitis." (PMID 33722194, 2021). "In previous studies, aside from high expression in epithelial keratinocytes, CCL27 levels were typically high in the superficial plexus of dermis during inflammatory processes such as atopic dermatitis, contact dermatitis, and healing of burn wounds." (PMID 29713456, 2018). "CCL27 is highly upregulated in inflammatory skin conditions such as atopic dermatitis, psoriasis, and contact dermatitis." (PMID 29713456, 2018). "Previous studies regarding the role of CCL27 in human pathology are primarily limited to atopic dermatitis; however, our data support a broader function involving MS inflammation and lymphocyte activation." (PMID 26295034, 2015). "CCL27 upregulation is primarily associated with the pathogenesis of atopic dermatitis; however, it is likely that its role is not exclusively restricted to skin inflammation." (PMID 26295034, 2015). "Conversely, CCL27/CCR10 are reduced in psoriatic lesions, alopecia areata and hidradenitis suppurativa, while a 2022 meta-analysis links higher to atopic dermatitis (AD) severity, point to disease specific regulation." (PMID 41050670, 2025). "Plasma concentrations of CCL27 and CCL22 were found to correlate positively with SCORing atopic dermatitis (SCORAD), objective SCORAD, % area affected, lichenification and disease intensity, and CCL27 also correlated positively with pruritus in AD patients (all p < 0.05)." (PMID 27077833, 2016).
melanoma (17 papers, 2010 to 2025). A malignant, usually aggressive tumor composed of atypical, neoplastic melanocytes. "The tumor injection of adenoviral vector encoding CCL27 attracted T cells and suppressed tumor growth in a murine melanoma model." (PMID 33381115, 2020). "Chemokines, specifically interactions between CCR10 and CCL27, have been implicated in melanoma metastasis to the skin." (PMID 24212610, 2010). "In melanoma, high CCL27 expression in the supratumoral epidermis is associated with longer tumor-free survival, whereas CCL27 downregulation in metastases and advanced SCC/BCC may represent an immune evasion strategy." (PMID 41050670, 2025). "In B16BL6 melanoma model, intratumorally delivery of an adenoviral vector encoding CCL27 and other chemokines (AdRGD), enhanced activated T cell recruitment and inhibited tumor growth, optimal antitumor efficacy may be achieved when combining with systemic effector T cell activation." (PMID 41050670, 2025). "This is in sharp contrast to its usual role as an important receptor for T-cell homing to cutaneous tissue, with its ligand, CCL27, produced by keratinocytes in the skin but also expressed by melanoma cells." (PMID 34830780, 2021). "One study employed an adenoviral vector to deliver chemokine CCL27 into tumors in a mouse model of B16BL6 melanoma and observed considerably increased recruitment of T cells." (PMID 33381115, 2020). "This suggests that despite the local accumulation of CCL27, CCR10-expressing T cells are unable to infiltrate CCL27-expressing melanoma lesions and these T cells are therefore restricted to circulate in the periphery." (PMID 30420855, 2018). "In contrast to benign lesions where CCL27 is expressed at low levels, many primary melanoma lesions express substantial amounts of this chemokine." (PMID 30420855, 2018). "The exposure of the ligand CCL27 to the melanoma cells leads to activation of Akt and phosphatidylinositol-3-kinase and protects the cells from apoptosis." (PMID 24259307, 2013). "Interactions between CCR10 and CCL27 are thought to mediate metastasis to the skin, supported by the observation that neutralizing antibodies to CCL27 can block formation of B16 melanoma in mouse ear skin." (PMID 24212610, 2010). "Given that cSCC exhibits significantly lower lymph node metastatic potential compared to breast cancer and melanoma, this finding suggests that CCL27 may play a role in the differential lymphatic metastasis capabilities among various cancers." (PMID 40296873, 2025). "CCL27, a chemokine involved in immune cell recruitment and lymphangiogenesis, has been shown to be upregulated in several cancers, including breast cancer and melanoma, where it contributes to tumor metastasis by promoting lymphatic spread." (PMID 40296873, 2025). "CCL27 has also been reported to be highly expressed in squamous cell epithelial cells and melanoma cells, and NPC is non- squamous type; in the latter, it may be involved in invasion and metastasis." (PMID 29295705, 2018). "Thus, CCL27/CCR10 contributes to the growth of melanoma cells by the activation of PI3K/Akt pathway and by evading the host anti-tumor response." (PMID 24259307, 2013). "However, another study hypothesised that T cells expressing CCR10 are unable to infiltrate melanoma lesions expressing CCL27." (PMID 37170733, 2023). "Hence, CCR10 engagement by locally produced CCL27 facilitates melanoma progression, most likely through activation of PI3K/Akt, which may allow melanoma cells to escape host immune antitumor killing mechanisms." (PMID 24212647, 2011). "The CCR10/CCL27 axis plays a significant role in tumour development, which is illustrated by the link between CCR10 overexpression in primary melanoma cells and increased regional lymph node metastasis." (PMID 37170733, 2023). "CCL27, a chemokine expressed in the epidermis by normal keratinocytes, seems to interact with the chemokine receptor CCR10, which is expressed in melanoma cells." (PMID 37833981, 2023).
melanoma (continued). "When CCL27 was added, signalling through CCR10 led to activation of the Akt and PI3K pathways, enabling melanoma cells to resist Fas-mediated apoptosis, a key mechanism in tumour cell clearance." (PMID 34830780, 2021). "Most chemokines were expressed intracellularly in all melanoma cell lines (CXCL9, CXCL11, CXCL12, CCL19, CCL21 and CCL27)." (PMID 24559071, 2014). "In vitro, exposure of CCR10-B16 cells to CCL27 led to rapid activation of Akt, which resulted in resistance of CCR10-B16 cells to cell death induced by melanoma antigen-specific cytotoxic T cells." (PMID 24212647, 2011). "The major chemokine/chemokine receptor interactions occurring in melanoma development and progression include the CXCR4/CXCR7/CXCL12, CXCR3/CXCL9,10,11, CXCR1,2/CXCL8, CCR2/CCL2, CCR4/CCL17,22, CCR5/CCL5, CCR7/CCL21 and CCR10/CCL27 axes." (PMID 37170733, 2023). "Another crucial factor in melanoma metastasis to the skin is represented by the interactions between chemokines C-C motif chemokine receptor 10 (CCR10) and C-C motif chemokine ligand 27 (CCL27)." (PMID 37833981, 2023). "In addition to promoting melanoma metastasis to the lymph nodes, the CCR10/CCL27 axis is also involved in mediating tumour proliferation, invasion, and immune escape, thus directly correlating with cancer progression." (PMID 37170733, 2023). "CXCL8, CXCL9, CXCL10, CCL27, and C3AR1 have known immunomodulatory roles in melanoma." (PMID 35008167, 2021). "Their results suggest that in human melanomas CCR10 and CCL27 may act on the ability of neoplastic cells to grow, invade tissue, disseminate to lymph nodes and to escape the host immune response." (PMID 24559071, 2014). "CCL27 is a chemokine expressed constitutively in the epidermis by normal keratinocytes, and is thought to interact specifically with the chemokine receptor CCR10, which is expressed on melanoma cells." (PMID 24212610, 2010).
COVID-19 (16 papers, 2020 to 2025). A disease caused by infection with severe acute respiratory syndrome coronavirus 2. "For example, severe COVID-19 was linked to changes in IL-13, IL6 and IL-1B, and multiple chemokines (e.g. CCL20, CCL27, CXCL10)." (PMID 36171541, 2022). "Previous studies reported that COVID-19 is frequently associated with a massive production of 14 cytokines including IFN-γ, IL-1RA (IL1RN), IL-2RA, IL-6, IL-10, IL-18, HGF, MCP-3 (CCL7), MIG (CXCL9), M-CSF (CSF1), G-CSF (CSF3), MIG-1a (CCL3), CTACK (CCL27), and IP-10 (CXCL10)." (PMID 34262555, 2021). "Six chemokines (CXCL9, CXCL10, CCL4, CCL5, CCL27, and CXCL12) and eight interleukins (IL-1Ra, IL-2Ra, IL-3, IL-5, IL-9, IL-12p40, IL-15, and IL-16) were increased in both PLWH/COVID-19 and COVID-19-only." (PMID 41516165, 2025).
breast carcinoma (8 papers, 2018 to 2025). "Another study identified that breast cancer patients showed elevated plasma levels of cytokines CCL27 and macrophage migration inhibitory factor (MIF) following two cycles of Dox." (PMID 38987722, 2024). "CCR10 expression was discovered to be elevated in breast cancer cells, and the CCL27/CCR10 axis eventually promoted breast cancer cell invasion and migration via elevating MMP-7." (PMID 36250005, 2022). "C-c motif chemokine ligand 27 (CCL27), a chemokine primarily expressed by keratinocytes, and its enhanced expression activate the extracellular signal-regulated kinase 1/2 (ERK1/2) pathway and in turn overexpress MMP-7 leads to cell invasion and migration of breast cancers." (PMID 36250005, 2022).
inflammatory skin disease (7 papers, 2016 to 2024). Inflammatory skin disorders covers a broad category that includes many conditions ranging in severity, from mild itching to grave medical health complications These disorders are common in people of all ages and races. "Increased CCL27 within the skin regulates CLA+ T lymphocyte cutaneous trafficking; therefore, high serum levels of CCL27 are commonly found in inflammatory skin diseases." (PMID 28138328, 2016).